EEF1AKMT1 (EEF1A lysine methyltransferase 1)
Description:
Protein N-lysine methyltransferase that selectively catalyzes the trimethylation of EEF1A at 'Lys-79'.
Synonyms: N6AMT2; ESP13; eEF1A-KMT
Tractability: Antibody: the Human Protein Atlas places it where antibodies can reach. PROTAC: ubiquitination databases record sites on it.
Gene: Protein-coding gene on chromosome 13 (20,727,970 to 20,773,961, reverse strand). Ensembl gene ENSG00000150456.
Subcellular location: Cytoplasm
Subcellular location (Human Protein Atlas): Cytosol; Plasma membrane
Pathways (Reactome):
Metabolism of proteins: Protein methylation
Gene Ontology:
Molecular function: protein-lysine N-methyltransferase activity; methyltransferase activity; nucleic acid binding; S-adenosylmethionine-dependent methyltransferase activity
Biological process: positive regulation of translational elongation
Cellular component: cytosol; cytoplasm
Genetic constraint (gnomAD): Loss-of-function variants: 19 observed, 23.86 expected, observed/expected ratio (o/e) 0.8, 90% interval 0.56 to 1.17. The upper end of that interval is the gene's LOEUF score, 1.17, which puts it in group 5 of 6, group 1 being the genes least tolerant of losing a copy. Missense variants: 246 observed, 272.18 expected, observed/expected ratio (o/e) 0.9, 90% interval 0.81 to 1. Synonymous variants: 109 observed, 101.19 expected, observed/expected ratio (o/e) 1.08, 90% interval 0.92 to 1.26.
Homologues: Orthologues: chimpanzee EEF1AKMT1 (99% identical), rat Eef1akmt1 (82% identical), mouse Eef1akmt1 (81% identical), macaque EEF1AKMT1 (80% identical), guinea pig EEF1AKMT1 (77% identical), dog EEF1AKMT1 (73% identical), rabbit EEF1AKMT1 (72% identical), pig EEF1AKMT1 (71% identical), tropical clawed frog eef1akmt1 (64% identical), zebrafish eef1akmt1 (50% identical), Caenorhabditis elegans M142.8 (43% identical), Drosophila melanogaster CG9154 (37% identical).